NFE2L2 (NFE2 like bZIP transcription factor 2)
Diseases named in the same sentence as NFE2L2 in open-access papers (continued):
Sharing a sentence is not in itself a finding about the gene and the disease.
systemic lupus erythematosus (3 papers, 2016 to 2024). An autoimmune multi-organ disease typically associated with vasculopathy and autoantibody production. "The ssGSEA results showed that the complement and coagulation pathways, Legionellosis, Malaria, Pertussis, Systemic lupus erythematosus (SLE), etc., were enriched in the high GLS and high NFE2L2 expression groups." (PMID 38062233, 2023).
alcoholic liver diseases (2 papers, 2021 to 2025). A disorder caused by damage to the liver parenchyma due to alcohol consumption. "For example, Nfe2l2/Nrf2 enhances fibrosis during the chronic stage of alcoholic liver disease, which may explain the surprising positive correlation of Nfe2l2/Nrf2 with fibrosis in this study." (PMID 35111154, 2021).
bladder transitional cell carcinoma (2 papers, 2022). The most common morphologic subtype of urinary bladder carcinoma (over 90% of cases). "NFE2L2 is also directly involved in the stabilization of the hybrid epithelial/mesenchymal state in RT4 urinary bladder transitional cell papilloma and UM-UC-1 bladder transitional cell carcinoma." (PMID 36231068, 2022).
breast tumors (2 papers, 2016 to 2024). "To validate the identified association of high NFE2L2 mRNA expression levels with a favourable patient outcome within an independent cohort we analysed 176 breast tumour tissue samples from our local biobank." (PMID 27770790, 2016). "We found a positive correlation between ZMYND8 and NFE2L2 mRNAs in human breast tumors and 28 other types of human cancers from TCGA cohort." (PMID 38488001, 2024). "In the test set we measured the NFE2L2 mRNA expression levels in 176 breast tumour tissues by quantitative real-time reverse transcription PCR (qRT-PCR)." (PMID 27770790, 2016). "The analysis of these samples revealed that NFE2L2 mRNA was significantly higher expressed in normal breast tissue compared to breast tumor tissue of the same patient (p < 0.001)." (PMID 27770790, 2016). "Nevertheless, our data indicate a predictive relevance of NFE2L2 mRNA expression levels in breast tumour tissue for patient survival." (PMID 27770790, 2016). "Genetic mutations in NFE2L2 and KEAP1 are uncommon in human breast tumors." (PMID 38488001, 2024).
colon adenocarcinoma (2 papers, 2020 to 2021). "Next, we searched the TCGA database and found that the NRF2 (NFE2L2) gene was positively correlated with the Warburg enzymes LDHA, PGK1, and HK2 in colon adenocarcinoma." (PMID 34094899, 2021).
dementia (2 papers, 2022 to 2023). Loss of intellectual abilities interfering with an individual's social and occupational functions. "Observed associations of polymorphisms in CAT, GSTP1, NFE2L2 and KEAP1 with dementia support the importance of antioxidative mechanisms in AD." (PMID 36829875, 2023). "Among antioxidative genes, CAT, GSTP1, NOS1, NFE2L2, and KEAP1 were associated with dementia or AD." (PMID 36829875, 2023). "Multiple effects of NFE2L2 and KEAP1 on dementia and AD were found in our study." (PMID 36829875, 2023).
dry eye (2 papers, 2020). "RS9 induced Nfe2l2 activation and Nfe2l2-targeted genes, reduced oxidation, and ameliorated symptoms of dry eye using in vitro and in vivo models." (PMID 32320433, 2020). "In summary, our results indicate that RS9 induces NFE2L2-targeted genes, reduces oxidation, and ameliorates the symptoms of dry eye in in vitro and in vivo models." (PMID 32320433, 2020). "However, the efficacy of NFE2L2 activator on dry eye remains to be examined." (PMID 32320433, 2020). "Because oxidative stress has an important role in the pathology of dry eye, the NFE2L2 activator, RS9 is expected to recover the symptoms of dry eye." (PMID 32320433, 2020).
endometriosis (2 papers, 2023 to 2024). The growth of functional endometrial tissue in anatomic sites outside the uterine body. "Analysis of endometrial stromal cells from individuals with endometriosis identified NFE2L2 and SMAD4 as the top two transcription factors controlling gene expression during decidualization." (PMID 38402336, 2024). "On the other hand, regulation of genes by the NFE2 Like BZIP Transcription Factor 2 (NFE2L2) and SMAD4 transcription factors was highly enriched in the endometriosis dataset." (PMID 38402336, 2024).
glomerular disease (2 papers, 2020 to 2023). "In the context of glomerular disease, there have only been a handful of studies published regarding NFE2L2 stress response pathways in podocytes." (PMID 37681897, 2023). "We evaluated the podocyte expression of NFE2L1, Nuclear Factor Erythroid 2-related Factor 2 (NFE2L2), and NAD(P)H:quinone Oxidoreductase (NQO1) in 127 human glomerular disease biopsies using multiplexed immunofluorescence and image analysis." (PMID 37681897, 2023).
goiter (2 papers, 2020 to 2024). Enlargement of the thyroid gland usually caused by lack of iodine in the diet, hyperthyroidism, or thyroid nodules. "VEGFA and NFE2L2 also showed elevated expression in the tumor- and goiter-adjacent tissues." (PMID 32824922, 2020). "VEGFA and NFE2L2 showed high expression levels in the tumor and goiter." (PMID 32824922, 2020). "We found higher levels of VEGFA and NFE2L2 transcripts and the VEGFA protein in goiter and PTC samples than in normal tissue." (PMID 32824922, 2020). "In relation to the goiter, only miR-612 expression presented a negative correlation with NFE2L2 expression." (PMID 32824922, 2020).
gout (2 papers, 2022 to 2025). A condition characterized by painful swelling of the joints, which is caused by deposition of urate crystals. "PTGS2, CASP8, NFE2L2, and CD274 were identified as key pyroptosis-related genes associated with gout." (PMID 36291136, 2022). "miR-16-5p, miR-128-3p, miR-20a-5p, and miR-155-5p can potentially influence pyroptosis and the occurrence and development of gout by affecting the expression of the PTGS2, CASP8, NFE2L2, and CD274 genes." (PMID 36291136, 2022). "Experimental validation revealed that PTGS2 and NFE2L2 were significantly upregulated, and CASP8 and CD274 were significantly downregulated in gout." (PMID 36291136, 2022).
hypopharyngeal squamous cell carcinoma (2 papers, 2023 to 2025). "In hypopharyngeal squamous cell carcinoma (HPSCC), ALKBH5-mediated m6A demethylation regulates the post-transcriptional modulation of NFE2L2/NRF2." (PMID 40271153, 2025). "In hypopharyngeal squamous cell carcinoma, IGF2BP2-involved m6A modification stabilizes NFE2L2/NRF2 mRNA, contributing to ferroptosis resistance." (PMID 37554271, 2023).
ischemia (2 papers, 2016 to 2024). A hypoperfusion of the BLOOD through an organ or tissue caused by a PATHOLOGIC CONSTRICTION or obstruction of its BLOOD VESSELS, or an absence of BLOOD CIRCULATION. "In mice, Nfe2l2 also seems to protect from ferroptosis induced by intestinal ischemia/reperfusion, but the role of NFE2L2 in ferroptosis regulation beyond cultured cancer cells is generally less well understood." (PMID 39025451, 2024).
laryngeal squamous cell carcinoma (2 papers, 2022 to 2025). A squamous cell carcinoma that arises from the larynx. "For example, increased NFE2L2 and TMB pathway changes were linked to radiation resistance in laryngeal squamous cell carcinoma (LSCC), and NLRP3 activation could promote carcinogenesis and chemoresistance in HNSCC, and ATP7B upregulation promoted chemoresistance of HNSCC." (PMID 36620545, 2022).
Leukoencephalopathy (2 papers, 2017 to 2020). This term describes abnormality of the white matter of the cerebrum resulting from damage to the myelin sheaths of nerve cells. "Furthermore, patients with de novo missense mutations in NFE2L2 that lead to accumulation of Nrf2 and increased expression of Nrf2-related genes present with leukoencephalopathy and diminished myelin content." (PMID 33261626, 2020). "Moreover, Nfe2l2-null mice were found to have vacuolar (spongiform) leukoencephalopathy with widespread astrogliosis." (PMID 29018201, 2017).
malaria (2 papers, 2018 to 2023). Malaria is a serious and sometimes fatal disease caused by a parasite that commonly infects a certain type of mosquito which feeds on humans. "Our results revealed significant enrichment of the complement and coagulation pathways, Legionellosis, Malaria, Pertussis, and SLE in the high GLS and high NFE2L2 expression groups." (PMID 38062233, 2023).
nonalcoholic fatty liver disease (2 papers, 2023 to 2024). "The results revealed significant correlations between dihydrolipoamide s-acetyltransferase (DLAT), dialectical behavior therapy (DBT), metal regulatory transcription factor 1 (MTF1), nonalcoholic fatty liver disease (NFE2L2), and developmental language disorder (DLD)." (PMID 38673957, 2024).
pancreatic adenocarcinoma (2 papers, 2020 to 2024). "Additionally, low expression levels of HMOX1 and NFE2L2 correlate with extended survival in patients with pancreatic adenocarcinoma." (PMID 39337472, 2024). "Analyzing data publicly available in KMplot, both NFE2L2 and HMOX1 expression are significantly (p = 4.16 × 10−48 and p = 7.81 × 10−54, respectively) upregulated in pancreatic adenocarcinomas compared with non-cancerous pancreatic tissue." (PMID 39337472, 2024).
pneumonia (2 papers, 2022 to 2025). An acute, acute and chronic, or chronic inflammation focally or diffusely affecting the lung parenchyma, caused by an infection in one or both of the lungs (by bacteria, viruses, fungi, or mycoplasma.). "Key molecules, such as nuclear factor erythroid 2-related factor 2 (NFE2L2 or NRF2), glutathione, catalase, hemopexin, and superoxide dismutase, regulate this process and are vital for managing oxidative stress in severe pneumonia cases." (PMID 41583455, 2025).
prostate tumor (2 papers, 2010 to 2023). "Oxidative stress can suppress NFE2L2 expression through hypermethylation of CpG islands present in the NFE2L2 promoter, as has been shown in prostate tumors." (PMID 37627486, 2023).
retinal degeneration (2 papers, 2022 to 2023). Degeneration of the retina. "Additionally, given the complexity and the degree of crosstalk between various immune pathways, other transcription factors (TFs), such as Hmox1, NFkB, and NFE2L2, might also interact with the C3a-C3ar1 pathway and be involved in retinal degeneration." (PMID 36110094, 2022).
sarcoma (2 papers, 2019 to 2020). A usually aggressive malignant neoplasm of the soft tissue or bone. "However, we find that MS‐275 enhances ROS indirectly in sarcoma cells by non‐transcriptionally inhibiting YB‐1‐mediated translation of NFE2L2 encoding the antioxidant master regulator, NRF2." (PMID 31668005, 2019).
Spinocerebellar ataxia type 3 (2 papers, 2020 to 2024). "For instance, G. inflata extract has been documented to reduce spinocerebellar ataxia type 3 (SCA3) by increasing the nuclear factor erythroid 2-related factor 2-antioxidant-responsive elements (NFE2L2-ARE), coactivator 1α (PPARGC1A), and the peroxisome proliferator-activated receptor γ activities." (PMID 32106571, 2020).
adrenal tumor (1 paper, 2025). "Genetic mutations are common in PMEC, and in this case, molecular typing of the lung tumor tissue, adrenal tumor tissue, and plasma samples all revealed the presence of BRAF p.V600E, AKT1, and NFE2L2 mutations." (PMID 40896440, 2025). "In this case, NGS of the lung tumor tissue, adrenal tumor tissue, and plasma revealed positive BRAF p.V600E, AKT1, and NFE2L2 mutations, which are common genetic mutations." (PMID 40896440, 2025).
Age-related cataract (1 paper, 2024). A type of cataract (opacification of the lens) that forms during the course of aging. "NFE2L2 is then phosphorylated and translocates into the nucleus, where it forms heterodimers with MAF, also associated with age-related cataracts." (PMID 39594457, 2024). "NFE2L2 transcriptional regulation is also modified by CITED2 (Cbp/p300 interacting transactivator with Glu/Asp rich carboxy-terminal domain 2), also associated with age-related cataracts." (PMID 39594457, 2024). "The T allele of rs13053109 in the promoter region of CRYAA is associated with increased risk of age-related cataracts and shows increased binding by KLF10 with consequent decrease in CRYAA transcription, providing indirect support for the role of the NFE2L2 pathway in age-related cataractogenesis." (PMID 39594457, 2024).
alcoholic cirrhosis (1 paper, 2022). "Single nucleotide polymorphism (SNP) rs35652124 variation in the transcription factor nuclear factor erythroid-related factor 2 (Nrf2)-encoding gene nuclear factor erythroid 2-related factor 2 (NFE2L2) is a potential genetic marker for susceptibility to alcoholic cirrhosis." (PMID 36077080, 2022).
anaplastic thyroid carcinoma (1 paper, 2022). "In PTC and anaplastic thyroid carcinoma, somatic KEAP1 and NFE2L2 mutations activating the Nrf2 pathway were discovered." (PMID 36686463, 2022).
aortic aneurysm (1 paper, 2021). A ruptured aneurysm located in the wall of the proximal portion of the descending aorta proceeding from the arch of the aorta. "Animal experiments using angiotensin II-induced aortic aneurysm model in mice showed that NFE2L2 gene deficiency increased the risk of development and rupture of aortic aneurysm." (PMID 34336095, 2021).
aortic atherosclerosis (1 paper, 2014). A atherosclerosis that involves the aorta. "NFE2L2 knockout mice exhibit ∼50% reduction in the degree of aortic atherosclerosis compared with the wild-type littermates; thus in this light a SNP that attenuates NFE2L2 expression or activity is indeed likely to have the protective potential for cardiovascular morbidity and mortality in humans." (PMID 24790085, 2014).
apical periodontitis (1 paper, 2025). "Additionally, NFE2L2 has been implicated in mitochondrial biogenesis disorders that promote refractory apical periodontitis." (PMID 40909264, 2025). "Notably, NLRP3 and NFE2L2 have previously been associated with apical periodontitis." (PMID 40909264, 2025).
asthenozoospermia (1 paper, 2025).
bone cancer (1 paper, 2018). A primary or metastatic malignant neoplasm affecting the bone or articular cartilage. "The top upstream regulators in the bone cancer pain model are shown inFigure 8A (p-value of overlap <0.05, ANOVA) and includes cytokine IFNG (activation z-score 1.9); growth factor LEP (activation z-score 0.4); and transcription regulator NFE2L2 (activation z-score 1.9)." (PMID 30079380, 2018).
brain tumour (1 paper, 2024). "Primary grade IV brain tumour is accompanied with a poor survival, as NFE2L2 is upregulated." (PMID 39248438, 2024).
carcinoid (1 paper, 2019). "Despite the literature evidence, to exclude this possibility we analyzed all carcinoid cohorts, searching for somatic alterations in the whole coding region of the KEAP1 gene and in the Neh2 domain of the NFE2L2 gene." (PMID 31126053, 2019).
cerebral edema (1 paper, 2021). "An important observation from our results is the overall higher expression of these transcriptional regulators, namely PPARG, REL, and NFE2L2 in PBMC at a delayed time point (>72 h), which falls within the time point of progressive cerebral edema after ICH." (PMID 33564466, 2021).
Chagas cardiomyopathy (1 paper, 2024). A disease of the cardiac muscle developed subsequent to the initial protozoan infection by trypanosoma cruzi. "Recent studies have found the involvement of NFE2L2 pathway inhibition by the mtROS in the evolution of Chagas cardiomyopathy, and enhancing the same pathway is currently being studied as one of the potential therapeutic options." (PMID 39280489, 2024).
Chagas disease (1 paper, 2021). A parasitic infection caused by Trypanosoma cruzi. "In the context of Chagas disease, T. cruzi-infected cardiomyocytes and human chagasic hearts show increased mRNA levels, but a decreased nuclear localization of PGC-1α-coactivated transcription factors such as NRF1, NRF2, and NFE2L2." (PMID 34976301, 2021).
chronic thyroiditis (1 paper, 2022). "Also, genetic interactions between minor alleles in the selenoprotein S gene (SELENOS) and the nuclear factor erythroid 2-related factor 2 gene (NFE2L2) increase chronic thyroiditis incidences." (PMID 36686463, 2022).
dilatation (1 paper, 2022). "One animal study showed that Nfe2l2-knockout mice had lower LPPs after vaginal dilatation compared to wild-type C57BL/6J mice and this suggests that this antioxidant gene inducer is a potential protective factor in the development of SUI." (PMID 35328824, 2022).
dysplasia (1 paper, 2017). A usually neoplastic transformation of the cell, associated with altered architectural tissue patterns.
endotoxemia (1 paper, 2019). "Recent work suggest that Nfe2l2 (nuclear factor, erythroid derived 2, Like 2; also known as NRF2) contributes to increase the metabolic activity and the expansion of Gr1+ CD11b+ MDSCs during endotoxemia." (PMID 30873175, 2019).
enteropathy (1 paper, 2026). "Mice fed a WD for 12 weeks developed enteropathy and loss of colonic motility, which was reversed by adeno-associated virus-mediated (AAV-mediated) overexpression of the transcription factor NFE2L2, preventing ferroptosis and restoring redox balance to enteric neurons." (PMID 42222886, 2026).
ependymoma (1 paper, 2021). A WHO grade II, slow growing tumor of children and young adults, usually located intraventricularly. "By elucidating core transcriptional regulatory circuitries from the set of gained enhancers, we identified several key TFs, including RXRA, NFE2L2, IRF2, RELA, etc., involved in cell growth and migration, some of which were also revealed to have tumor-promoting functions in ependymoma and RCC25,26." (PMID 34294701, 2021).
Failure to thrive (1 paper, 2023). Failure to thrive (FTT) refers to a child whose physical growth is substantially below the norm. "More recently, clinical studies have identified patients with inborn activating mutations in NRF2 (NFE2L2), and these patients manifest with a multisystem disorder that involves a failure to thrive, immunodeficiency, and neurological symptoms." (PMID 37216554, 2023).
gastrointestinal stromal tumor (1 paper, 2020). "In contrast, RB1 that was regarded as a tumor suppressor gene in gastrointestinal stromal tumors and was identified as a monotonically increasing gene, while three oncogenes including NFE2L2, ABL1, and LASP1 were identified as monotonically decreasing genes." (PMID 33273919, 2020).
laryngeal tumours (1 paper, 2023). "The peculiar genomic characteristics also include loss‐of‐function alterations of the chromatin modifier NSD1, WNT pathway genes AJUBA and FAT1, and activation of oxidative stress factor NFE2L2, mainly in laryngeal tumours." (PMID 37322598, 2023). "On the other hand, majority of the laryngeal tumours harboured alterations in Wnt pathway genes, a chromatin modifier (NSD1) and activation of NFE2L2, an oxidative stress factor." (PMID 37322598, 2023).
lung carcinoid (1 paper, 2019). "Here we describe the results obtained from the first comprehensive genetic and epigenetic profile of KEAP1 and NFE2L2 genes in a collection of lung carcinoid tumors." (PMID 31126053, 2019). "Additionally, we perform the first epigenetic profile of KEAP1 promoter region in lung carcinoid tissues together with the genetic screening of the KEAP1 and NFE2L2 genes and LOH analysis." (PMID 31126053, 2019).